H2BC12L (H2B clustered histone 12 like)
Description:
Core component of nucleosome. Nucleosomes wrap and compact DNA into chromatin, limiting DNA accessibility to the cellular machineries which require DNA as a template. Histones thereby play a central role in transcription regulation, DNA repair, DNA replication and chromosomal stability. DNA accessibility is regulated via a complex set of post-translational modifications of histones, also called histone code, and nucleosome remodeling. Has broad antibacterial activity. May contribute to the formation of the functional antimicrobial barrier of the colonic epithelium, and to the bactericidal activity of amniotic fluid.
Synonyms: H2B/s; H2BFS; H2BS1
Tractability: PROTAC: UniProt records ubiquitination sites on it; ubiquitination databases record sites on it.
Gene: Protein-coding gene on chromosome 21 (43,565,182 to 43,565,648, forward strand). Ensembl gene ENSG00000234289.
Subcellular location: Nucleus; Chromosome
Subcellular location (Human Protein Atlas): Nucleoplasm; Cytosol
Pathways (Reactome):
Gene expression (Transcription): B-WICH complex positively regulates rRNA expression; DNA methylation; ERCC6 (CSB) and EHMT2 (G9a) positively regulate rRNA expression; MLL4 and MLL3 complexes regulate expression of PPARG target genes in adipogenesis and hepatic steatosis; NoRC negatively regulates rRNA expression; PRC2 methylates histones and DNA; RNA Polymerase I Promoter Escape; RNA Polymerase I Promoter Opening; RUNX1 regulates genes involved in megakaryocyte differentiation and platelet function; RUNX1 regulates transcription of genes involved in differentiation of HSCs; Regulation of endogenous retroelements by KRAB-ZFP proteins; Regulation of endogenous retroelements by Piwi-interacting RNAs (piRNAs); Regulation of endogenous retroelements by the Human Silencing Hub (HUSH) complex; SIRT1 negatively regulates rRNA expression; Transcriptional regulation by small RNAs
DNA Repair: Cleavage of the damaged purine; Cleavage of the damaged pyrimidine; Nonhomologous End-Joining (NHEJ); Processing of DNA double-strand break ends; Recognition and association of DNA glycosylase with site containing an affected purine; Recognition and association of DNA glycosylase with site containing an affected pyrimidine; Recruitment and ATM-mediated phosphorylation of repair and signaling proteins at DNA double strand breaks
Cell Cycle: Condensation of Prophase Chromosomes; Deposition of new CENPA-containing nucleosomes at the centromere; G2/M DNA damage checkpoint; Inhibition of DNA recombination at telomere; Packaging Of Telomere Ends
Chromatin organization: CHD1 and CHD2 subfamily; CHD6, CHD7, CHD8, CHD9 subfamily; ChAHP complex assembly; Interaction of NuRD complexes with transcription factors; NuRD complex assembly
Developmental Biology: Activation of anterior HOX genes in hindbrain development during early embryogenesis; Chromatin modifications during the maternal to zygotic transition (MZT); Replacement of protamines by nucleosomes in the male pronucleus; Transcriptional regulation of granulopoiesis
Signal Transduction: Activated PKN1 stimulates transcription of AR (androgen receptor) regulated genes KLK2 and KLK3; Estrogen-dependent gene expression; Formation of the beta-catenin:TCF transactivating complex; Pre-NOTCH Transcription and Translation
and 11 more pathways
Gene Ontology:
Molecular function: DNA binding; structural constituent of chromatin; protein heterodimerization activity
Biological process: antibacterial humoral response; antimicrobial humoral immune response mediated by antimicrobial peptide; defense response to Gram-positive bacterium; innate immune response in mucosa; substantia nigra development; chromatin organization
Cellular component: extracellular region; nucleus; nucleosome; chromosome
Homologues: Orthologues: chimpanzee H2BC12 (98% identical), dog H2BC15 (98% identical). Paralogues in human: H2BC12 (98% identical), H2BC10 (98% identical), H2BC11 (98% identical), H2BC4 (98% identical), H2BC6 (98% identical), H2BC7 (98% identical), H2BC8 (98% identical), H2BC15 (97% identical), H2BC21 (97% identical), H2BC5 (97% identical), H2BC9 (97% identical), H2BC13 (96% identical), and 9 more.
Diseases named in the same sentence as H2BC12L in open-access papers:
H2BC12L is named in the same sentence as 17 diseases in open-access papers, as found by Europe PMC text mining. Sharing a sentence is not in itself a finding about the gene and the disease.
H2BC12L shares sentences with these, for which no sentence is quoted: cancer (7 papers); tumor (6); breast carcinoma (3); colon cancer (2); lung carcinoma (2); acute lymphoblastic leukemia (1); autoimmune disease (1); Autoimmunity (1); diabetes (1); familial hypercholesterolemia (1); fungal infection (1); glioma (1); hepatoma (1); infertile (1); leukaemia (1); ovarian carcinoma (1); Sepsis (1).